BRAF (B-Raf proto-oncogene, serine/threonine kinase)
Diseases named in the same sentence as BRAF in open-access papers (continued):
Sharing a sentence is not in itself a finding about the gene and the disease.
Papillary Craniopharyngioma (continued). "This case represents the youngest patient reported to date with a papillary craniopharyngioma that has been validated by molecular analysis, revealing a BRAF V600E mutation." (PMID 30069716, 2019). "This is the youngest case published to date of papillary craniopharyngioma with a confirmed BRAF V600E mutation." (PMID 30069716, 2019). "Recently, a dramatic tumor reduction has been reported in a patient with BRAFV600E mutated, multiply recurrent papillary craniopharyngioma using a combination therapy of BRAF inhibitor dabrafenib and MEK inhibitor trametinib." (PMID 28918496, 2017). "The BRAF V600E mutation was recently described as a genetic hallmark of papillary craniopharyngiomas." (PMID 27409178, 2016). "All control cases of papillary craniopharyngiomas showed evidence of BRAF V600E mutation either by immunohistochemistry or by pyrosequencing." (PMID 27409178, 2016). "The recent identification of BRAF mutations in papillary craniopharyngioma changes the paradigm in treating this (primarily adult) tumor because of the availability of BRAF V600E-specific inhibitors." (PMID 25990246, 2015). "Papillary craniopharyngiomas frequently exhibit BRAF V600E mutations." (PMID 41310495, 2025). "Recent research uncovered the BRAF mutation in papillary craniopharyngiomas, leading to new targeted treatments that may reduce the need for invasive procedures." (PMID 39456573, 2024). "With regard to papillary craniopharyngioma, a BRAF V600 mutation is detected in 95% of cases." (PMID 36979325, 2023). "AC is characterized by alterations in the Wnt/b-catenin pathway, mainly involving the central regulatory gene CTNNB1, while papillary craniopharyngioma is mostly driven by the V600E mutation in the BRAF gene, which activates the mitogen-activated protein kinase (MAPK) signaling pathway." (PMID 37728836, 2023). "Nearly all cases of papillary craniopharyngioma demonstrate BRAF V600E mutations, which may be amenable to treatment with anti-BRAF agents and can lead to dramatic tumor response." (PMID 35323318, 2022). "However, a simple biopsy prior to submitting the patient to a high-risk procedure should be considered to identify a subset of patients with papillary craniopharyngiomas with BRAF mutation." (PMID 35757402, 2022). "Interestingly, none of the postnatal pups exhibited pituitary tumours such as papillary craniopharyngioma, which is known to harbour somatic BRAF p.V600E mutations." (PMID 33795686, 2021). "Surprisingly, papillary craniopharyngiomas have BRAF mutations and patients may respond dramatically." (PMID 31748891, 2020). "Whether a RCC can acquire a BRAF mutation and transform into a papillary craniopharyngioma remains hypothetical." (PMID 30069716, 2019). "In patients with papillary craniopharyngioma, 95% of tumors have BRAF V600E mutations." (PMID 31466300, 2019). "Moreover, since most papillary craniopharyngiomas harbor the BRAF V600E oncogenic mutation, a novel alternative is drug inhibition of the encompassing mitogen-activated protein kinase (MAPK) pathway controlling cell division, differentiation, and invasion." (PMID 30069716, 2019). "Interestingly, papillary craniopharyngioma is also caused by BRAF Val600Glu instead of a CTNNB1 mutation." (PMID 28658279, 2017). "Furthermore, in papillary craniopharyngioma, BRAF V600E mutation could confer proliferative advantage to SOX2+ tumour cells." (PMID 39456573, 2024). "Also, it has been shown recently that activating mutations in BRAF disrupt the hypothalamo–pituitary axis development leading to hypopituitarism, while somatic mutation of BRAF pV600E is a driver of benign tumor, papillary craniopharyngioma and is identified in corticotroph adenomas." (PMID 37435457, 2022). "Papillary craniopharyngioma (PCP), defined by near-universal BRAF V600E mutations, exhibits profound and rapid responses to combined BRAF and MEK inhibition, with objective response rates exceeding 90% in prospective studies." (PMID 41898146, 2026).
Papillary Craniopharyngioma (continued). "Alternatively, one case report of a single patient’s experience describes empiric treatment with BRAF/MEK inhibition alone of a presumed papillary craniopharyngioma with excellent radiographic and neuroendocrinologic outcomes." (PMID 39976897, 2025). "This review has elucidated the molecular characteristics of papillary craniopharyngioma (PCP) and explored core mechanisms driving tumorigenesis, particularly emphasizing the role of the BRAF V600E mutation." (PMID 40696244, 2025). "The combination of BRAF and MEK inhibitors has demonstrated high efficacy in managing papillary craniopharyngiomas and other tumors with BRAF-V600E mutations, highlighting the potential of precision medicine." (PMID 40113789, 2025). "This review provide a comprehensive overview of the molecular biology and therapeutic advances regarding papillary craniopharyngiomas (PCP), with a particular focus on the pivotal role of the BRAF V600E mutation in its pathogenesis." (PMID 40696244, 2025). "An extreme example of the potential success of BRAF ± MEK inhibition in papillary craniopharyngioma is demonstrated in a case report of a patient with radiographic evidence of craniopharyngioma, but refusal of surgical resection or biopsy for tissue diagnosis." (PMID 39976897, 2025). "In papillary craniopharyngioma, targeting BRAF-V600E and MEK with monotherapy and combined therapies are currently being investigated." (PMID 40042714, 2025). "RCCs with intense squamous metaplasia can mimic papillary craniopharyngiomas in microscopy, macroscopy, and radiology, yet as mentioned, BRAF V600E is positive in these lesions." (PMID 39939491, 2025). "In a recent phase 2 study from 2023, 16 patients with papillary craniopharyngioma were treated with the BRAF-MEK inhibitor combination vemurafenib-cobimetinib." (PMID 41310495, 2025). "Nevertheless, in rare cases of uncertainty, a BRAF V600E stain can be applied as nearly all papillary craniopharyngiomas express this mutant protein whereas developmental cysts are uniformly negative." (PMID 39939491, 2025). "The response to BRAF inhibitors in papillary craniopharyngioma has shown promise, but the tumor recurs shortly after treatment interruption in most cases." (PMID 31712784, 2019). "The current finding and the previous case report indicate promising results for the postoperative treatment with BRAF (dabrafenib) and MEK inhibitors (trametinib) of BRAFV600E mutated papillary craniopharyngiomas." (PMID 28918496, 2017). "This is the second case report on a therapeutic response to combined BRAF and MEK-targeted therapy in a recurrent papillary craniopharyngioma with genetically confirmed BRAFV600E mutation." (PMID 28918496, 2017). "All papillary craniopharyngiomas should be tested for BRAF V600E." (PMID 39664200, 2024). "While BRAF inhibitors could benefit patients with papillary craniopharyngiomas, targeted therapies for the adamantinomatous type remain in development." (PMID 37221626, 2023). "Molecular genetic research recently revealed that adamantinomatous craniopharyngioma has a CTNNB1 mutation but no BRAF V600E mutation, and papillary craniopharyngioma has a BRAF V600E mutation but no CTNNB1 mutation." (PMID 36913010, 2023). "Furthermore, a recent case report showed a radical tumor reduction in the papillary craniopharyngioma following a combination therapy with BRAF (dabrafenib) and MEK inhibitors (trametinib)." (PMID 28918496, 2017). "While empiric treatment in this unique case was effective, tissue diagnosis is still recommended for formal diagnosis and molecular and genetic analysis, as approximately 5% of papillary craniopharyngiomas have not demonstrated the BRAF V600E mutation, as described in the original genomic analysis." (PMID 39976897, 2025). "Hence, staining with antibodies that document a BRAF V600E mutation is not proof that these structures own these mutations and originate from the same cellular lineage as papillary craniopharyngiomas." (PMID 39939491, 2025).
Papillary Craniopharyngioma (continued). "Papillary craniopharyngioma is a solid or partially cystic, non-keratinizing squamous epithelial tumor that develops in the infundibulotuberal region of the third ventricle floor, most often in adults, and is characterized by BRAF p.V600E mutation." (PMID 36913010, 2023). "However, this feature may not stem from the fact that papillary craniopharyngiomas and RCCs originate from the same cells, as BRAF mutations are not shown with gene sequencing in RCCs." (PMID 39939491, 2025). "In 2015, the first report demonstrated significant therapeutic efficacy using combined BRAF and MEK inhibition in a case of multiply recurrent papillary craniopharyngioma (PCP)." (PMID 40696244, 2025). "The study provides preliminary prospective data in favor of BRAF and MEK inhibition for the treatment of papillary craniopharyngioma." (PMID 39976897, 2025). "This is the first case report in the literature detailing concurrent radiation therapy with BRAF and MEK inhibitors for papillary craniopharyngioma." (PMID 37431357, 2023). "Patients over the age of 18 years with a histologically confirmed diagnosis of a BRAF-V600E driven papillary craniopharyngioma and no upfront radiation were eligible for this study." (PMID 40042714, 2025). "Subsequently, BRAF inhibition combined with the MEK inhibitor trametinib has shown a decrease in proliferation of tumor cells in vitro and in preclinical xenograft models and produced a dramatic response in a refractory papillary craniopharyngioma case." (PMID 31712784, 2019). "BRAF inhibitors, including vemurafenib and dabrafenib, have proved successful either alone or in conjunction with trametinib, an inhibitor of another MAPK member MEK, to treat adults with papillary craniopharyngioma, resulting in tumor shrinkage with good tolerability." (PMID 30069716, 2019). "Likewise, despite sharing histological similarities to a papillary craniopharyngioma, RCC was excluded by the absence of a BRAF point mutation." (PMID 30069716, 2019).
leukemia (40 papers, 2012 to 2025). A malignant (clonal) hematologic disorder, involving hematopoietic stem cells and characterized by the presence of primitive or atypical myeloid or lymphoid cells in the bone marrow and the blood. "Conversely, leukemia samples are characterized by a variegated expression of multiple BRAF transcript variants." (PMID 40415485, 2025). "Some examples include the combined effects that induce fatality of leukemia cells, attenuate tumor growth of BRAF-mutated colorectal cells, and enhance the antitumor effects of MEK1/2 treatment in RAS-mutated lung cells." (PMID 33035223, 2020). "They share overlapping clinical, cytomorphologic, and immunophenotypic features, posing difficulties in the reliable distinction between the splenic B-cell lymphomas and leukaemias, except for HCL harboring the characteristic BRAF p.V600E mutation." (PMID 40282427, 2025). "We recommend further studies to investigate if the risk of developing leukemia after RAI treatment is heightened in the presence of any specific mutations, such as BRAF or KRAS." (PMID 39796657, 2024). "We then tested the expression level of BRAF in several leukemia cell lines." (PMID 38178263, 2024). "In one patient, the BRAF mutation was lost during relapse, while the rest of RAS-related genes (KRAS and WT1), and the KMT2A::MLLT3 fusion persisted (Case No. 2), suggesting that the BRAF mutation may not be the driver mutation for this leukemia." (PMID 38791222, 2024). "Therefore, we think that leukemia induced by BRAF(V600E) and pTENKO in B lymphocytes may mimic an aggressive subtype of human HCL that has a high AKT signaling and a poor prognosis." (PMID 37543582, 2023). "Besides well-known cases such as BRAF (V600E), KRas (G12D, G13D) or PIK3CA (G118D), we derived previously uncharacterized hotspot mutations such as SF3B1 (K700E) found in eight breast tumors and one leukemia sample." (PMID 31345222, 2019). "For early naïve culture we used 5iLA conditions (MEK inhibitor, GSK3 inhibitor, ROCK inhibitor, BRAF inhibitor and SRC inhibitor with human leukemia inhibitor factor (hLIF) and Activin A;)." (PMID 37702917, 2023). "Except for BRAF p.V600E, the genetic hallmark of HCL, no genetic mutation or chromosomal abnormality is pathognomonic for other splenic B-cell lymphomas and leukaemias." (PMID 40282427, 2025). "The available leukemia cell lines JVM3 (K601N BRAF) and SIG-M5 (V600E BRAF) were used for comparison of these two mutations since no pancreatic neuroendocrine cell lines exist that express these mutations (and attempts to culture the patient’s cancer cells were unsuccessful)." (PMID 31158244, 2019). "Based upon this, it is tempting to speculate that BRAF fusion within a ventricular zone progenitor cells blocks normal differentiation “locking” the cell into a permanent embryonic state, similar to that process described in pediatric leukemia." (PMID 33206716, 2020).
serous ovarian cancer (40 papers, 2007 to 2026). "BRAF mutations can occur in low-grade serous ovarian carcinomas (LGSCs) and their presence is associated with an earlier stage of disease at presentation, better prognosis, and they are less frequently seen in advanced or recurrent LGSC." (PMID 39941911, 2025). "In terms of low-grade serous tumors, an A to T substitution in BRAF has been identified in 36–68% of low-grade serous ovarian cancers and is associated with improved prognosis." (PMID 30087267, 2018). "The contributions of BRAF to endometriosis and endometriosis-associated ovarian cancers, specifically, low-grade serous ovarian cancers are understudied." (PMID 30087267, 2018). "We reported earlier that KRAS or BRAF mutations were quite common in low-grade serous ovarian carcinomas but rare in conventional high-grade serous carcinomas." (PMID 19018267, 2008). "Furthermore, KRAS mutations are more common in low-grade serous ovarian cancer along with BRAF mutations." (PMID 38730733, 2024). "Low-grade serous ovarian carcinoma exhibits a unique genetic profile characterized by KRAS/BRAF mutations compared to high-grade serous carcinoma, thus MEK inhibitors might be appropriate for the treatment of this malignancy." (PMID 39139644, 2024). "The frequency of KRAS/BRAF mutations associated with low-grade serous ovarian carcinoma (LGSC)/serous borderline tumors (SBTs) in Japan is unknown." (PMID 31892193, 2019). "Low-grade serous ovarian cancers typically have either BRAF or KRAS mutation." (PMID 30018258, 2018). "Notably, KRAS and BRAF mutations in serous borderline tumor or low-grade ovarian serous carcinoma are generally mutually exclusive." (PMID 23554638, 2010). "In relation to low-grade serous ovarian cancer, BRAF inhibitors as single agents were approved for the treatment of BRAF-mutated tumors." (PMID 40977811, 2025). "The target genes analyzed in this study (e.g., ITGB1, TIMP3, and BRAF) were selected based on their strong prognostic relevance identified from cBioPortal survival analyses of high-grade serous ovarian carcinoma." (PMID 41294900, 2025). "Typically, low-grade serous ovarian carcinoma has few somatic mutations, which are mainly found in genes associated with the mitogen-activated protein kinase pathway such as KRAS, BRAF and NRAS." (PMID 29132324, 2017). "BRAF is the downstream effector of KRAS, which was reported to be common mutation (28–35 %) in serous borderline (SB)/low grade serous ovarian cancer (LGS-OvCa)." (PMID 26490766, 2015). "Patients harboring BRAF mutations or dysregulation of the MAPK and PI3K pathways, particularly those with low-grade serous ovarian carcinoma, may significantly benefit from BRAF or MEK inhibitors." (PMID 40862791, 2025). "The absence of KRAS/BRAF mutation also distinguishes BIN-67 from low-grade ovarian serous carcinomas and mucinous cancers." (PMID 23433318, 2013). "In low-grade serous ovarian carcinoma the mitogen-activated protein kinase (MAPK) pathway is activated, a kinase cascade that mediates the transmission of growth signals into the nucleus, via mutations in KRAS and BRAF, the upstream regulators of the MAPK pathway." (PMID 33043759, 2020).
serous ovarian cancer (continued). "This point also provides a rationale for exploring MAPK kinase (MEK) inhibitors in the treatment of low-grade serous ovarian cancer, such as selumetinib, trametinib or dabrafenib, which are MEK1 and MEK2 inhibitors (MEKi) that indirectly inhibit the BRAF and KRAS pathways." (PMID 32679669, 2020). "To elucidate the post-transcriptional mechanisms contributing to the differential expression of prognostic genes identified in Section 3.1, we next investigated microRNAs (miRNAs) that may regulate TIMP3, BRAF, and ITGB1 in high grade serous ovarian cancer (HGSOC)." (PMID 41294900, 2025). "BRAF, a serine/threonine kinase and central effector of the MAPK/ERK pathway, though rarely mutated in serous ovarian carcinoma (SOC), may contribute to tumor progression through non-mutational overexpression." (PMID 41294900, 2025).